MSLN (mesothelin)
Diseases named in the same sentence as MSLN in open-access papers (continued):
Sharing a sentence is not in itself a finding about the gene and the disease.
cancer (continued). "This shows that the expression of mesothelin and its relation to prognosis and cancer aggressiveness is cancer specific." (PMID 35326701, 2022). "In this type of immunotherapy for MSLN-positive cancers, Listeria monocytogenes, a Gram-positive bacterium, can be used as a vector." (PMID 35565412, 2022). "Mesothelin (MSLN) mediates cellular adhesion and is normally only expressed in mesothelial cells; however, when dysregulated in cancer, MSLN promotes proliferation, migration and invasion, making it an attractive target for TTC-based therapy." (PMID 36726355, 2022). "Previous studies indicate that aberrant MSLN expression promotes cancer cell proliferation, local invasion and metastasis." (PMID 36059490, 2022). "MSLN is a strong candidate for anti-cancer therapy with recombinant immunotoxins due to its distinctive expression in human malignancies." (PMID 36358290, 2022). "MSLN is overexpressed in various cancer types, including mesothelioma, lung cancer, pancreatic cancer, ovarian cancer, breast cancers, and meningiomas." (PMID 35954348, 2022). "Due to its limited expression in healthy tissues, MSLN has grown into a therapeutic target for different types of cancers and therapeutic strategies, such as vaccines, immunotoxins, monoclonal antibodies, antibody-drug conjugates or CAR-T cells." (PMID 36009489, 2022). "These include: CDH1, MUC1, THBS4, and MSLN for PEs related to cancer; ADA2, CXCL10, and WARS for TB-PEs; CRP, S100A9, and VIM for parapneumonic PEs; and C9, LDHA, HPX, LDHB, and C3 for benign-PEs." (PMID 35197508, 2022). "ERC/mesothelin contributes to cancer progression by modulating cell signals that regulate proliferation and apoptosis." (PMID 35565327, 2022). "MSLN is a glycoprotein de novo expressed in a number of cancers, including PaC, which makes it attractive as a diagnostic and therapeutic target." (PMID 36009489, 2022). "MSLN is shown to have a very limited expression in normal tissues, thus making it a very attractive candidate for cancer therapy." (PMID 36387279, 2022). "To overcome the disadvantages and enhance the penetration in tumors, we developed a 27 kDa human single chain variable fragment (scFv) of IgG against the mesothelin (MSLN) overexpressed in various cancer cells." (PMID 36291173, 2022). "Based on our results, MSLN can be a key molecular target for new gene-targeted cancer therapy, especially in the direction of immunotherapy." (PMID 35692779, 2022). "This review summarizes the current knowledge on mesothelin’s function, its role in cancer, and opportunities for immunotherapeutic targeting of mesothelin." (PMID 35326701, 2022). "When released from the cell membrane, MSLN can be detected in sera from patients with different cancers." (PMID 36009489, 2022). "Mesothelin silencing by siRNA and microRNA decreased cell viability and invasiveness in multiple cancer types by reduced ERK1 and PI3K/AKT signaling, further confirming that mesothelin overexpression activates pro-survival signaling." (PMID 35326701, 2022). "For these reasons, various types of anti-MSLN therapies have been developed, including antibodies, antibody-drug conjugates (ADCs), immunotoxins, cancer vaccines, and chimeric antigen receptor (CAR)-T cell immunotherapies." (PMID 35795680, 2022). "Conversely, MSLN was rare in cancers of the breast, kidney, thyroid gland, soft tissues, and prostate." (PMID 35565412, 2022). "MSLN is known to be an oncogenic immunomodulatory protein in many types of cancers, for example ovarian, adenocarcinoma, and most importantly BC." (PMID 36387279, 2022). "Immunotherapy-based strategy to target human MSLN-expressing cancer cells has been developed by Dr. Pastan and colleagues, pioneers in the field of cancer research." (PMID 36358290, 2022). "There is evidence that mesothelin can be used as a new cancer biomarker and as a target molecule for gene therapy." (PMID 35565412, 2022).
cancer (continued). "A 20-base-pair promoter region, Canscript, containing an SP1-like element and MCAT element, has been identified as responsible for mesothelin expression in certain cancers." (PMID 35326701, 2022). "MSLN is a potential target for cancer immunotherapy, considering its low expression on normal cells and high expression in a variety of solid malignancies." (PMID 36059490, 2022). "Mesothelin have been studied as a biomarker for targeted therapy including antibody-based drugs, cancer vaccine, and chimeric antigen receptor T cell therapies in several types of solid tumors." (PMID 33832498, 2021). "Both measurements were carried out on cultured human cancer cell lines of N87 and H226, both with MSLN expressed on the cell surface." (PMID 34326410, 2021). "Until recently, CA125 (mouse Muc16) remained the only known ligand of MSLN that activates Src/Akt signaling in cancer cells." (PMID 34966784, 2021). "Our analysis of 12,679 cancers generated a ranking order of cancers according to their frequency of MSLN expression." (PMID 33917081, 2021). "By taking the advantage of CAR-T cells, we generated CAR-T cells that are not only targeting MSLN positive cancer cells but also secreting PD-1 antibodies to block PD-1 and promote the cytotoxicity of T cells." (PMID 33589520, 2021). "Mesothelin (MSLN) is an attractive target for cancer immunotherapy because it is highly expressed in a broad spectrum of solid tumors but present at low levels on normal tissues such as peritoneal, pleural, and pericardial mesothelial surfaces." (PMID 34381179, 2021). "MSLN is known to bind to mucin 16 (MUC16/CA125), which is expressed by MPM cells and is associated with cancer progression and aggressiveness." (PMID 34439085, 2021). "Alternatively, anti-MSLN CAR T cells can be used in combination with oncolytic viruses targeting TGF-β-expressing cancer cells." (PMID 33588928, 2021). "MSLN is differentially expressed between normal and cancer cells, thus making it a strong candidate for anti-cancer therapy with recombinant immunotoxins (RITs)." (PMID 34966784, 2021). "Depletion of MMP-7 or inhibition of p38 activity abolishes MSLN-mediated cancer cell motility and invasion." (PMID 34966784, 2021). "Mesothelin (MSLN) is a glycosylphosphatidylinositol-anchored protein which is involved in several mechanisms of cancer pathogenesis such as increased cell proliferation and survival, but its biological functions remain uncertain." (PMID 34769211, 2021). "Mesothelin (MSLN) is an attractive candidate of targeted therapy for several cancers, and hence there are increasing needs to develop MSLN-targeting strategies for cancer therapeutics." (PMID 34326410, 2021). "TC-210 is able to recognize and bind to MSLN on cancer cells, thus stimulating the cytotoxic activity of T cells." (PMID 33588928, 2021). "Given its involvement in tumorigenic processes and its marginal expression in healthy tissue, mesothelin has been extensively investigated as a therapeutic target for cancer." (PMID 34522225, 2021). "The results showed that the anti-MSLN-sP CAR-T cells were better able to attack target cancer cells and penetrate through the HA-containing matrix than conventional anti-MSLN CAR-T cells." (PMID 34326835, 2021). "MSLN expression has been linked to matrix metallopeptidase 9 (MMP-9) expression at the invading edges of tumors, illustrating its role in promoting cancer invasion." (PMID 34439085, 2021). "To target region I, we selected SS scFv and its affinity-matured derivative SS1, based on the validated efficacy and safety of their immunotoxin (SS1-immunotoxin, SS1P) and antibody (MORAb-009, Amatuximab) formats in human cancer patients bearing MSLN+ tumors." (PMID 33418877, 2021). "These cancers with a positivity rate of 40% or higher in our study appear to be the best candidates for targeted anti-MSLN therapy." (PMID 33917081, 2021).
cancer (continued). "In a clinical trial (NCT02414269) performed by a team from the Memorial Sloan Kettering Cancer Center, anti-MSLN inducible caspase 9-M28z (iCasp9M28z) CAR-T cells are being tested for safety and feasibility." (PMID 33025047, 2021). "Targeting mesothelin (MSLN) is an attractive cancer therapeutic strategy, which has led to a large number of clinical trials of treating diverse cancers." (PMID 34326410, 2021). "Since its discovery in 1992 as a cancer antigen, the mechanism of human MSLN signaling remains unresolved." (PMID 34966784, 2021). "Conversely, MSLN is known to be overexpressed in several human cancers including mesotheliomas, ovarian, pancreatic and gastric." (PMID 34830322, 2021). "Given its limited expression on normal tissues and high abundance on cancer cells, mesothelin is an attractive target." (PMID 34226685, 2021). "The overexpression of MSLN promotes cancer cell invasion via matrix metalloproteases 7 and 9 induction and promotes cancer cell survival and proliferation via the NF-KB pathway." (PMID 33670777, 2021). "N87 and Capan-2 cancer models were selected because both are important human cancers with limited treatment options and both cancer cells express MSLN on the cell surface." (PMID 34326410, 2021). "Anti-MSLN Ab-immunotoxins, developed for cancer therapy, can potentially be used to target human MSLN+ aPFs for treatment of cholestatic fibrosis." (PMID 34966784, 2021). "The Amatuximab derived SS and SS1 scFvs targeting region I of human MSLN were highly effective in mediating THV infection of MSLN+ human cancer cells." (PMID 33418877, 2021). "For these reasons, our research team has demonstrated the utilization of 89Zr-labeled anti-MSLN-scFv as a potential rapid PET probe for MSLN-positive cancer diagnosis." (PMID 33670777, 2021). "In ex vivo experiments, MSLN-targeted CAR-T cells exerted substantial inhibitory effects on cancer cell proliferation and invasion." (PMID 34790207, 2021). "MSLN has been attracting attention as a cancer differentiation antigen due to its high expression in several malignancies and is currently being evaluated as a target for antibody- and vaccine-based therapies for cancer." (PMID 33670777, 2021). "MSLN facilitates cancer cell attachment on mesothelial surfaces, MMP upregulation and autocrine signalling—playing multiple roles in PDAC metastasis." (PMID 33546207, 2021). "Collectively, these results indicated that these CAR-T cells had intrinsic target-dependent cytotoxic activity and cytotoxicity of Tandem-CAR T cells on FOLR1- or MSLN-positive cancer cells was greater than single-target CAR-T cells in vitro." (PMID 34803504, 2021). "Antibody–drug conjugates (ADCs) targeting MSLN have been demonstrated to be a viable strategy in treating MSLN-positive cancers." (PMID 34326410, 2021). "This MSLN scFv-LGA-PEI polymer is ready for loading TNAs and specifically delivering to cancer cells with the expression of MSLN." (PMID 34577541, 2021). "Induction of the CD3 downstream signaling pathway anti-MSLN/CD3 bsAbs allowed us to measure T-cell-induced killing of MSLN-positive cancer cell lines at 24 and 48 h of co-culturing PBMCs and MSLN-positive cancer cells at an effector:target ratio of 10:1." (PMID 32143496, 2020). "We would expect these inhibitors would also improve the activity of antibody drug conjugates, Chimeric antigen receptor (CARs), and other antibody-based therapies that are being developed to target cancers that express MSLN." (PMID 33262421, 2020). "Cancers exhibiting MSLN-positive immunostaining had significantly higher MSLN mRNA expression (median MSLN/GAPDH ratio, 0.031; range, 0.025–0.037) than the MSLN-negative ones (median MSLN/GAPDH ratio, 0.0053; range, 0.0022–0.0085; P < 0.0001)." (PMID 33196692, 2020). "In brief, the functional mechanisms of anti-MSLN mAb include not only ADCC but also alteration of intracellular signalling in cancer cells through endocytosis." (PMID 32061257, 2020).
cancer (continued). "The fact that membrane bound Mesothelin levels are increased in several human cancers and the protein is accessible from the extracellular space makes it a target for novel Mesothelin directed antibody-based therapies." (PMID 32815024, 2020). "To investigate the MSLN protein expression profile in cancer cell lines, we performed flow cytometry using an anti-hMSLN rat antibody (R&D systems)." (PMID 32143496, 2020). "As mesothelin is overexpressed in various types of cancer, it is an attractive target for therapeutic antibodies." (PMID 32143496, 2020). "Mesothelin was recognized as an attractive candidate for targeted cancer therapy due to its limited expression in normal tissue and high expression in cancer tissue." (PMID 32050659, 2020). "To test the performance of the method, we ran several simulations on mock pancreatic sample profiles containing reference cancer cell profiles with either high or low MSLN expression." (PMID 32616712, 2020). "In another study, human mesothelin-targeted mRNA was introduced in human peripheral lymphocytes and investigated in human in vitro and murine in vivo cancer models, with designed to express human mesothelin." (PMID 32899932, 2020). "Pre-clinical and clinical studies increasingly show that aberrant MSLN expression plays a role in cancer progression." (PMID 32612258, 2020). "Mesothelin is a differentiation antigen that is highly expressed in a number of human cancers including mesotheliomas, pancreatic and lung adenocarcinomas, and ovarian and breast carcinomas." (PMID 33178203, 2020). "The differential expression pattern of MSLN in normal and cancer tissues makes it a promising target for diagnosis and therapeutic applications." (PMID 32983962, 2020). "MSLN is an attractive target for cancer therapy, and a growing number of clinical trials are currently exploring diverse MSLN-targeted strategies, including the use of immunotoxin, antibody drug conjugates, monoclonal antibodies, and CAR-T cells." (PMID 32143496, 2020). "MSLN plays a pivotal role in cancer cell survival/proliferation by NF-kB activation which induces IL-6 expression." (PMID 33344222, 2020). "The typical expressing pattern of MSLN in normal and cancer tissues makes it a promising target for diagnosis and therapeutic applications." (PMID 32983962, 2020). "Yet, in our in vitro cytotoxic assay, we found that IPI‐549‐treated and vehicle CAR T cells killed approximately 50% of the mesothelin‐expressing cancer cells while CAL‐101‐ and TGR‐1202‐treated T cells killed more (∼75%) of them." (PMID 32383488, 2020). "Mesothelin (MSLN, 630 amino-acid residues) is a tumor-associated antigen which is overexpressed in many human cancers." (PMID 33339164, 2020). "Due to its differential expression between cancer and normal tissues and its role in tumorigenesis, MSLN can be regarded as a potential target for OC." (PMID 32983962, 2020). "Specifically, MSLN promotes cancer proliferation and apoptosis resistance through NF-kB activation, while GPC-3 promotes cancer proliferation through sulfatase/Wnt- signaling pathway." (PMID 33344222, 2020). "In a clinical trial using anti-mesothelin immunotoxins, the majority of side effects were attributed to on-target, off-cancer cell binding due to mesothelin’s expression on healthy tissue." (PMID 32575752, 2020). "The restricted expression of MSLN in normal tissue and its frequent expression in cancers make MSLN an excellent target for antibody-based therapies." (PMID 33262421, 2020). "Accessing three independent transcriptomic data sets confirmed that serous cancer subtypes (including high and low-grade carcinomas) have higher levels of MSLN than other subtypes of EOC." (PMID 32612258, 2020). "Aberrant expression of MSLN plays a central role in cancer cell proliferation, invasion and metastasis through activating PI3K, ERK, and MAPK signaling pathways." (PMID 31209210, 2019).
cancer (continued). "In this case it would be the first instance of MSLN overexpression in the context of a disease process unrelated to cancer." (PMID 31222072, 2019). "Analogous to finding in cancer, we also observed increase in both bound and soluble MSLN in women with hydrosalpinx." (PMID 31222072, 2019). "MSLN was observed in several cancer types, meaning it represents an important therapeutic immunological target." (PMID 31430969, 2019). "The bacterium-based vaccine CRS-207, which uses a live-attenuated Listeria monocytogenes (Lm) strain ANZ-100 (Lm ΔactA/ΔinlB) engineered to express human MSLN, has been used to treat MSLN-positive cancers in clinical trials." (PMID 31463062, 2019). "MSLN is a cell-surface glycoprotein with normal expression in peritoneum, pleura, and pericardium, but with overexpression in a variety of cancers, including mesothelioma, pancreatic, lung, gastric, and ovarian cancers." (PMID 31209210, 2019). "Although the CAR T-cell therapies that target MDR of MSLN have been reported to inhibit cancer growth, the overall efficacy is still relatively low in vivo." (PMID 31209210, 2019). "MSLN is overexpressed in several human cancers, notably those characterized by aggressive phenotypes and poor prognosis such as mesotheliomas, pancreatobiliriary, ovarian, and lung carcinoma." (PMID 31354732, 2019). "Mesothelin (MSLN), a 40 kDa glycosyl-phosphatidyl inositol-linked (GPI) membrane glycoprotein, has been attracting growing interest in the field of cancer therapy." (PMID 31354732, 2019). "Anetumab ravtansine was demonstrated to be rapidly internalized by cancer cells and exhibited the preferred intracellular trafficking route into lysosomes upon binding to mesothelin." (PMID 30344925, 2018). "Several features of MSLN make it a useful candidate for cancer therapy, including that it is well-internalized, enabling it to be a good target for immunotoxins." (PMID 30134520, 2018). "This approach hasbeen successfully used both in vitro and in vivoto study CD19- and mesothelin-specific CARs.Mesothelin-specific CARs have been subsequently successfully applied to treatpancreatic cancer." (PMID 30116611, 2018). "A number of studies, including Phase 1 and II clinical trials, are ongoing to target mesothelin expressing cancers." (PMID 29474384, 2018). "Live attenuated Listeria monocytogenes-expressing mesothelin is being evaluated as an anti-cancer vaccine." (PMID 29474384, 2018). "SS1P is the first generation of anti-mesothelin immunotoxins which has been tested in patients with mesothelin-expressing cancers." (PMID 30441807, 2018). "Upon specific binding to mesothelin on human cancer cell lines, the engineered Fn3 proteins internalized and co-localized to early endosomes." (PMID 29738555, 2018). "The aberrant expression of MSLN involves the aggressiveness and transformation of tumors through promoting cancer cell proliferation." (PMID 29707526, 2018). "MSLN is a cell-surface glycoprotein with presence in the sera of cancer patients as soluble MSLN-related peptide (SMRP)." (PMID 30031396, 2018). "An 18-bp enhancer sequence, CanScript, located −65 to −46 bp 5′ of one of three transcriptional start sites in the promoter region of the MSLN gene, was identified in cancer cell lines with aberrant overexpression of MSLN." (PMID 30134520, 2018). "Mesothelin is a cell surface protein that is overexpressed in numerous cancers, including breast, ovarian, lung, liver, and pancreatic tumors." (PMID 29738555, 2018). "We, herein, demonstrated that overexpressed Mesothelin mediates 1.1- to 19.4-fold greater CA125 re-absorption in insulin-treated cancer cells compared with that in control cells, while Mesothelin overexpression itself is also modulated by the PI3K-Akt pathway." (PMID 29716620, 2018). "This expression pattern makes mesothelin an attractive target for cancer therapy, and several agents targeting mesothelin are currently in clinical trials." (PMID 30333914, 2018).